CTLA4 (cytotoxic T-lymphocyte associated protein 4)
Diseases named in the same sentence as CTLA4 in open-access papers (continued):
Sharing a sentence is not in itself a finding about the gene and the disease.
tumor (continued). "The absence of CTLA-4 has been demonstrated to reduce the threshold for TCR ligation, increasing the presence of active tumor-reactive T cells." (PMID 40075727, 2025). "In vivo, localized ablation selectively suppressed tumor growth without systemic toxicity, increasing TNFRSF4+ while decreasing CTLA-4+ Treg subsets." (PMID 41208977, 2025). "In turn, tumor-specific T cells expressing Carmil2QE do not require CD28 engagement and thereby escape to both PD-1 and CTLA-4 inhibition." (PMID 40402149, 2025). "Whereas IACS-16898 monotherapy did not yield any antitumor responses and anti-PD-1 plus anti-CTLA-4 (ICT) alone induced hyperprogression, the combination of IACS-16898 with ICT significantly decreased RMC tumor growth." (PMID 41290625, 2025). "Our results show that strategically targeting TIM3, LAG3, TIGIT, CTLA4, IFITM, TREM2 and PD-1 in MMRd and also MMRp CRC tumors not only further limits tumor growth but can also significantly increase the complete elimination of tumors." (PMID 40027748, 2025). "Unlike PD-1 or CTLA-4, BTLA interacts bidirectionally with its ligand HVEM, forming a complex signaling network that shapes immune homeostasis within the tumor microenvironment." (PMID 41471273, 2025). "Evaluation of gene expression can provide insightful information about the tumor microenvironment.Until now, to our knowledge, the JAK2/STAT3/CTLA4 axis has not been investigated for tissue-specific gene expression at the mRNA levels in OSCC." (PMID 40092547, 2025). "Unlike PD-1/CTLA-4, inhibition of TIGIT in tumor therapy restores the immune function of T cells through multiple pathways." (PMID 40890162, 2025). "A recent neoadjuvant regimen involving simultaneous inhibition of PD-1, CTLA-4, and LAG-3 demonstrated durable tumor control in glioblastoma, with no recurrence at 17 months." (PMID 40950404, 2025). "This resulted in increased immune regulator molecules such as CTLA4, PDL1, Tim3, VISTA, LAG3, CD38, CD80, CD86, MHC Class II, and PD-L1 being presented on the surface of trogocytic tumor cells compared to non-trogocytic tumor cells." (PMID 40440354, 2025). "As the immune checkpoint blockade for CTLA4, PD1 and ligand PDL1 disrupts negative immune regulatory checkpoints to release pre-existing anti-tumor immune responses." (PMID 39769192, 2024). "Our data demonstrated that the anti-CTLA-4 antibody, but not the anti-GITR antibody DTA-1, can induce significantly improved tumor-specific antitumor effects in combination with vvDD-IL-9 treatment." (PMID 38473379, 2024). "Unlike treatment with the anti-CTLA-4 VHH (H11)-VHHkappa conjugate, the A12-VHHkappa conjugate induced tumor rejection in only a fraction of the animals." (PMID 39149504, 2024). "In cold tumors, tumor cells within the TME always express diverse immunosuppressive ligands, such as PD-L1 and CTLA-4, to inhibit antitumor immunity, resulting in a lack of immunogenicity and immune cell infiltration." (PMID 39695072, 2024). "In contrast to preclinical models of other tumor types, in RCC models, DR-18 enhanced the activity of anti–CTLA-4 but not anti–PD-1 treatment." (PMID 39561007, 2024). "When IR (8 Gy × 3) was combined with the immune checkpoint inhibitor (ICI) anti-CTLA-4, complete and durable regression of both the irradiated and non-irradiated mouse cell line TSA-derived tumor was observed." (PMID 38678042, 2024). "Tumor growth of individual treatment groups indicated that there was no significant differential tumor growth among IgG, anti‐CD8, and APG‐157 + anti‐CTLA‐4 + anti‐CD8 antibodies treated groups." (PMID 38686626, 2024). "Subsequently, we compared the expression of exhaustion related molecules in CD4+T cells and found that CD4+T cells in obese tumor samples had higher expression of TIGIT and CTLA4 molecules compared with non-obese tumor samples." (PMID 38311726, 2024).
tumor (continued). "The absence of anti-tumor activity of anti-PDL2, anti-CTLA4 and combination of anti-PDL1 and anti-CTLA4 further demonstrated that ICIs alone were unable to induce a robust immune response." (PMID 39199612, 2024). "Combination of RT with CTLA-4 or PD-1 blockade, which enables CD28 costimulation, further increased this Treg response and failed to improve tumor control." (PMID 38349740, 2024). "The essence of ICI is a branch of mAbs, specifically promoting anti-tumor T-cell responses and response factors by targeting negative regulatory proteins (ICP: CTLA-4, PD-1/PD-L1)." (PMID 39097732, 2024). "In vivo, the administration of PR-001573 significantly inhibited tumor growth with a TGI value of 100% and did not change the weight of hPD-L1-expressing colon cancer (MC38)-cell-grafted PD1- and CTLA4-transgenic female B6 mice." (PMID 38257366, 2024). "By contrast, T3-HDVax abrogated tumour rejection in all mice treated with anti-PD1 or anti-4-1BB, but did not ablate anti-CTLA4-induced tumour rejection." (PMID 39048822, 2024). "Since tumor cells failed to induce T cell responses, ICI (pembrolizumab (anti-PD-1), durvalumab (anti-PD-L1), and ipilimumab (anti-CTLA-4)) were added to the co-culture to improve anti-tumor reactions." (PMID 39075115, 2024). "When ICI were used to interfere with PD-1 and PD-L1, which was expressed on the majority of tumor cells, there was no improvement in anti-tumor response observed, even when these ICI where combined with anti-CTLA-4." (PMID 39075115, 2024). "Given the suppressed tumor microenvironment (TME), single ICIs like anti-CTLA4 and anti-PD1 have not demonstrated significant antitumor response rates." (PMID 39199637, 2024). "Anti-PD-L1 antibody alone showed a small regression in tumor growth with a limited improvement of survival in GL261-bearing mice, Anti-CTLA-4 treatment did not reduce tumor growth or animal survival." (PMID 36839777, 2023). "The antibodies anti-CTLA-4, anti-PD-L1 and anti-LAG-3 with anti-PD-L1 also strongly inhibited tumor growth and enhanced survival in the absence of PDT, albeit to a lesser extent." (PMID 36997666, 2023). "Inhibition of negative immune regulatory responses (by blocking PD-1 or CTLA-4 signaling) is the central tenant of ICI therapy and has been successful in improving immune destruction and clearance of multiple tumor types including RCC." (PMID 37173966, 2023). "Alternative ICs, including TIM3, can be considered as a potential therapeutic target to obtain more effective anti-tumor responses in patients not responding to PD1/PDL1 and CTLA4 inhibitors." (PMID 36761751, 2023). "Given the variation in the sensitivity of tumor patients to immunotherapy, we compared the expression levels of EFRGs between HCC patients who received PD-L1/CTLA-4 treatment and those who did not." (PMID 37575252, 2023). "In our research, well-known immune checkpoint molecules such as PD-1, PD-L1, CTLA-4, and LAG-3 were not highly expressed in the tumor tissues." (PMID 37511338, 2023). "Overexpression of PD-1, CTLA-4, and GITR also have negative effects on TILs, bolstering immunosuppression of the tumor." (PMID 37138880, 2023). "Interestingly, some studies suggest that neither knockout nor overexpression of PD-L1 in tumor cells affected the efficacy of PD-L1 inhibitors, but it is the PD-L1 located on immune cells (DCs, macrophages) that correlates with the efficacy of anti-PD-1 alone or in combination with anti-CTLA-4." (PMID 36845142, 2023). "Double positive (TIGIT+CTLA-4+) (IR-9) and triple positive (TIGIT+CTLA-4+TIM-3+) (IR-12) were highest among PD1+CD28+ T cells in periphery and did not increase in the tumor." (PMID 37898752, 2023). "While anti-PD-1 plus anti-CTLA-4 therapy alone did not lead to growth inhibition, the combination with exercise plus ICI therapy resulted in significantly delayed tumor growth." (PMID 37760634, 2023).
tumor (continued). "We can infer that, in addition to low CTLA-4 immunostaining in the lymph nodes and tumors, the presence of neoplastic mast cells in distant organs and peripheral blood, corresponding to cases No. 8 and No. 4, respectively, may be related to the promotion of tumor escape to other organs." (PMID 37370399, 2023). "Abrogation of negative immune feedback provided by the upregulation of CTLA4 on T cells and PD1 on B cells, T cells, and several other cells results in a durable anti-tumor response." (PMID 37259163, 2023). "Moreover, a high value of α1/α2 was also shown by mouse No.2 from the anti-CTLA-4-therapy group (the tumor volume of 191 mm3), which, despite the initially large tumor, demonstrated the tumor growth inhibition starting from day 11 and reduction in the tumor node size." (PMID 38435479, 2023). "CD274 expression was found to be down-regulated in tumor tissues (P < 0.05), while TIGIT, PDCD1, CTLA4 and LAG3 expression in tumor tissues were not statistically different." (PMID 36959799, 2023). "We finally showed that non-responders to anti-PD-1 and/or anti-CTLA-4 ICI therapies have lower IFNG, Merck18, CD274 and CD8 scores, and lower dysfunction of the tumor." (PMID 36389735, 2022). "NT2.5 cells were inoculated into the two mammary fat pads of FVB/N mice, which were divided into four groups: no treatment (Non), anti-PD-1 and anti-CTLA4 antibodies (P1C4), irradiation of the large tumor (Rad), and combination (R + P1C4) groups." (PMID 35763240, 2022). "Combination therapy did not improve CT-26 tumor response compared to CTLA-4 alone; suggesting the absence of a cumulative effect, and therefore the main response is due to the exclusive action of CTLA-4 itself." (PMID 35339889, 2022). "We found that besides TNFRSF4, Treg functional signature genes such as FoxP3, CTLA4, TIGIT, TNFRSF18 (GIRT), CCR8, LAYN, and MAGEH1 were also overexpressed in C11-Tregs-FoxP3 of treatment-naive and non-MPR tumor lesions, but not for MPR tumor lesions." (PMID 35831283, 2022). "The overexpression of CTLA4 and PD-L1 on the surface of CD8+ T cells promotes the exhaustion of the CD8+ T cells and thereby fails to exert anti-tumor immunity." (PMID 35571034, 2022). "In conclusion, tumor immunity was different according to the neoadjuvant therapy method and response, with CD86, CD4, and t/iCD8 expression, but not CTLA-4 and sCD8 expression, being significantly higher in the nCT-treated and poor response groups." (PMID 36428666, 2022). "First, local intratumoral injection of anti-CTLA-4 antibody or anti-GIRT mAb, not systemic delivery, has led to decreases in tumor size while inducing tumor regression at distant sites with few systemic effects." (PMID 34417572, 2022). "Upregulation of CTLA-4 and LAG3 molecules can initiate a negative feedback mechanism that creates an active immune environment in an inflamed tumor and can improve prognosis." (PMID 35434132, 2022). "As for T cell exhaustion, notable negative relationship between FXYD2 expression and CTLA-4, TIGIT, and BTLA persisted before and after tumor purity adjustment." (PMID 36313180, 2022). "Otherwise, the mRNA expression of LAG3, CTLA4, PD-1, PD-L1, and HAVCR2, tightly related to tumor immunosuppression or tolerance, were not significant differences in ACC with CENPFhigh, compared with CENPFlow (all p > 0.05)." (PMID 35123514, 2022). "FTY720 treatment partially reversed the antitumor effect of anti–PD-1 plus anti–CTLA-4 without influencing body weight, demonstrating the role of CTL tumor infiltration in the antitumor effects of ICIs." (PMID 35788116, 2022). "One mouse in the anti-CTLA4 + PRO group showed complete tumor clearance, while none in the anti-CTLA4 single treated group achieved tumor free status." (PMID 35017664, 2022). "These tolerogenic DCs present tumor antigen without proper costimulation (CD80/CD86), express inhibitory molecules (PDL1/CTLA4), and secrete immunosuppressive factors (TGF-β, IL-10, IL-27, NO, Arg, and IDO)." (PMID 35972798, 2022).
tumor (continued). "In contrast to the findings in normal lung tissue from our NSCLC patients, when we examined tumor tissue in this cohort, ACE2 expression did not correlate with levels of PD-L1, ICOS, CTLA-4, PD-1, and TIGIT." (PMID 36324736, 2022). "They expressed, for the most part, TIGIT, but did not express CTLA-4, which was expressed by PD-1hiCD39+ CD4 T cells at the tumor site." (PMID 35954341, 2022). "For example, anti-CTLA-4 mAbs ipilimumab and tremelimumab were found to increase the density of CD4+ and CD8+ T cells in tumor tissues but not deplete Tregs." (PMID 35345849, 2022). "Reportage of tumor RORC-Treg infiltration was calculated from the averaged, normalized levels of FOXP3, CTLA4, GITR, RORC and GATA3." (PMID 34681642, 2021). "PD-L1 protein levels were not detectable above the background in any tumor or tumor regions of interest (ROI), and CTLA4/PD-1 expression were below measurable levels in >90% of ROI." (PMID 34831389, 2021). "Although survival was significantly increased in the combination treatment group with anti-CTLA-4 and GPB730, we did not observe complete tumor regression which was possibly due to acquired resistance." (PMID 33786638, 2021). "In contrast, anti-PD-1, anti-CTLA-4, or even a combination of both failed to make any impact on LLC1 tumor growth." (PMID 34771674, 2021). "In contrast, neither of the inhibitors of the function of CTLA-4, PD-1, or HSP90 applied separately or in combination with each other appeared to significantly suppress the development of the tumor colonies." (PMID 34208396, 2021). "We did however not observe differences in tumor or spleen M-MDSCs or G-MDSCs levels between anti-CTLA-4 and the combination anti-CTLA-4 + GPB730 in this study." (PMID 33786638, 2021). "Interestingly, the addition of anti-CTLA-4 with either TGFβ1 or TGFβ3 inhibition, but not pan-TGFβ inhibition, had an even stronger effect in prolonging overall survival compared to isoform-specific TGFβ blockade alone but did not significantly affect tumor growth." (PMID 34789823, 2021). "We observe that combinations of anti-CTLA-4 and BEMPEG are powerful in eradicating micro-metastases but do not adequately control well-established macroscopic tumor sites." (PMID 33937052, 2021). "On the other hand, CTLA-4 expression and its relationship with tumor-infiltrating Tregs has not been characterized in ICC, and little is known about CTLA-4 and PD1/PD-L1 expression and interaction in ICC." (PMID 34526987, 2021). "Interaction of CTLA4 with CD86 inhibits T cell activation and is a key negative regulator of the immune response to tumor." (PMID 34316327, 2021). "The Phase II CONDOR study evaluated a combination of CTLA-4 and PD-L1 inhibitors, tremelimumab and durvalumab, in R/M HNSCC patients with no or low (<25%) PD-L1 expression in the tumor cells." (PMID 33477635, 2021). "CTLA-4 induces antiproliferation of T cells, Tregs activation and upregulation of IDO, playing a negative role in anti-tumor immune response." (PMID 34620200, 2021). "For instance, the ICI CTLA-4 is primarily influential in lymphoid tissue, as opposed to PD-1 ICI, which affects the tumor microenvironment." (PMID 34769156, 2021). "The combination of CTLA-4 and PD-1 blockade restored IL-2 production and CD8 T cell expansion in a murine model; however, no additional T cell infiltration into the tumor microenvironment was observed." (PMID 34769156, 2021). "CTLA-4 and OX40 are upregulated in tumor-infiltrating, but not peripheral, regulatory T cells (Tregs)." (PMID 34123841, 2021). "This was the reason why single-agent anti-PD-1, or anti-CTLA-4 antibody treatment or both together, failed to inhibit the growth of LLC1; T cells failed to infiltrate the tumor." (PMID 34771674, 2021). "Not surprisingly, blockade of both interactions: CTLA-4/B7-1 and B7-2 with anti-CTLA-4 antibody, or PD-1/PD-L1 with either anti-PD-1 or anti-PD-L1 antibody resulted in decreased tumor size in unimmunized mice." (PMID 32133048, 2020).
tumor (continued). "CTLA-4 expression was detectable at high levels on the surface of breast SK-BR-3 and prostate LNCaP cancer cells, at very low levels on MCF-7 tumor cells and H9c2 cardiomyoblasts, used as control non-neoplastic cells." (PMID 32024070, 2020). "In contrast to anti-CTLA-4, the expression of MHC-II (but not MHC-I) proteins by tumor and the presence of IFN-γ-mediated gene signatures were found to be associated with the positive responses to anti-PD-1 therapy in melanoma." (PMID 33194652, 2020). "Meanwhile, tumor-specific MHC-II expression in response to anti-PD-1 therapy was essential, but it is not effective with anti-CTLA-4 or combined immunotherapy." (PMID 32974156, 2020). "When TCR clones were tracked, anti-CTLA-4 drove polyclonal, rather than oligoclonal expansion of TCR clones within the tumor." (PMID 33163002, 2020). "In addition to the expression of CTLA-4 and PDCD1, tumor-infiltrating lymphocytes (TILs) express a number of other co-inhibitory receptors, including HAVCR2 and TIGIT, providing additional targets that could be exploited for inducing anti-tumor immune responses." (PMID 33585210, 2020). "First, we have reported that blocking the interaction between CTLA-4 and its cognate ligand CD80 and CD86 is neither necessary nor sufficient for anti-CTLA-4-induced tumor rejection." (PMID 31991588, 2020). "Despite increases in the total CD45+ tumor infiltrating immune cells, the percentage of CD4+ and CD8+ T cells were not changed by IL36 or combined administration of IL36 and CTLA-4 mAbs." (PMID 32351508, 2020). "We used a model in which inbred mice bearing tumors derived from monoclonal cancer cell lines respond dichotomously to anti-CTLA-4 and anti-PD-L1 ICT, with some mice experiencing complete tumor regression within days, and the others not responding to therapy." (PMID 33262762, 2020). "In this case, the MHCs class I would carry viral antigens ready to be recognized, but due to the immune escape activated by the tumor cells, with the production of ARG1, LAG3, and CTLA4, they do not recognize it." (PMID 32331228, 2020). "Ipilimumab (anti-CTLA-4) showed no significant survival benefit over placebo in CRPC patients, while pembrolizumab (anti-PD-1) did show anti-tumor activity but the response rates were low." (PMID 33034643, 2020). "Importantly, anti-tumor effects without adverse effects were achieved in CTLA-4 heterozygous mice, while both anti-tumor and adverse effects were observed only in homozygous mice, indicating distinct genetic requirement for the adverse effects and anti-tumor efficacy." (PMID 32570871, 2020). "An increased proportion of CD8+ T cells in the initial TILs supplemented with anti-CTLA-4 antibody compared to non-supplemented TILs secreted TNF and IFN-γ and expressed CD107a upon co-culture with autologous tumor cell lines." (PMID 32127601, 2020). "Early treatment with anti-CTLA4, but not with anti-PD-L1 or anti-RL, significantly attenuated RANK−/− tumor growth (66.7% of implanted tumors did not grow) compared with the isotype-treated control." (PMID 33303745, 2020). "As FACS analysis for PDL1, PD1, and CTLA4 was performed in the tumor without isolation of the possible cell types, it is unclear whether determining if detection at different time points is a function of changes in the expression of these markers on the tumor or immune cell populations." (PMID 32033171, 2020). "One patient (No 14) with tumor stage M1c had received anti-PD1 followed by BRAF inhibition with vemurafenib, and a third line combined anti-PD1 and anti-CTLA4 immunotherapy before treatment with T-VEC was induced." (PMID 32052079, 2020). "The right flank tumor was then injected with 30μg of the TLR9 agonist MGN1703 or PBS on days 3, 6 and 9 with or without concordant injection of 100μg of the CTLA-4 antibody 9D9-mIgG2a systemically." (PMID 31771649, 2019).